HMGA1P6 (high mobility group AT-hook 1 pseudogene 6)
Synonyms: formerly HMGA1L6
Gene: Processed pseudogene on chromosome 13 (23,134,174 to 23,134,564, forward strand). Ensembl gene ENSG00000233440.
Diseases named in the same sentence as HMGA1P6 in open-access papers:
HMGA1P6 is named in the same sentence as 13 diseases in open-access papers, as found by Europe PMC text mining. Sharing a sentence is not in itself a finding about the gene and the disease. The quoted sentences say what the papers report.
ovarian carcinoma (5 papers, 2019 to 2024). A malignant neoplasm originating from the surface ovarian epithelium. "By functioning as a competitive endogenous RNA (ceRNA) and causing an increase in the production of HMGA1 and HMGA2, HMGA1P6 mechanically increases the malignancy of ovarian cancer cells." (PMID 39337410, 2024). "We next transfected gradient concentration of HMGA1P6 plasmid into ovarian cancer cells and then evaluated HMGA1 and HMGA2 expression." (PMID 32127525, 2020). "Mechanistically, HMGA1P6 promoted ovarian cancer cell malignancy by acting as a ceRNA (competitive endogenous RNA) that led to enhanced HMGA1 and HMGA2 expression." (PMID 32127525, 2020). "MYC, which is commonly overexpressed in HGSOC and ovarian cancer cell lines was predicted with two binding sites on HMGA1P6 promoter region." (PMID 32127525, 2020). "We further demonstrated that HMGA1P6 was one of highly expressed pseudogenes in HGSOC which promoted ovarian cancer aggressiveness through modulating HMGA1/2." (PMID 32127525, 2020). "To explore the biological function of HMGA1P6 in ovarian cancer pathogenesis, we established stable cell lines with HMGA1P6 overexpression or knockdown." (PMID 32127525, 2020). "Collectively, these results indicate that HMGA1P6 acts as a ceRNA to regulate HMGA1/2 expression in ovarian cancer." (PMID 32127525, 2020). "We next tested the effect of HMGA1P6 on aerobic glycolysis in ovarian cancer cells." (PMID 32127525, 2020). "Our findings reveal that MYC may contribute to oncogenesis through transcriptional regulation of pseudogene HMGA1P6 in ovarian cancer." (PMID 32127525, 2020). "In addition, ectopic expression of HMGA1P6 enhanced the invasive capacity whereas knockdown of HMGA1P6 decreased invasion potential in ovarian cancer cells." (PMID 32127525, 2020). "Taken together, these data suggest that HMGA1P6 exhibit oncogenic potential in ovarian cancer." (PMID 32127525, 2020). "Collectively, our findings suggest that pseudogene HMGA1P6 could be a valuable prognosis marker and promising therapy target for ovarian cancer." (PMID 32127525, 2020). "Moreover, we measured the effect of HMGA1P6 on ovarian cancer cell migration by a high-content imager (Perkin Elmer) and analyzed by harmony software." (PMID 32127525, 2020). "We here show that MYC transactivates a novel transcript, HMGA1P6 in ovarian cancer." (PMID 32127525, 2020). "Moreover, growth curve analysis showed that HMGA1P6 overexpression dramatically enhanced the proliferation of ovarian cancer cells, while silencing HMGA1P6 induced an opposite effect." (PMID 32127525, 2020). "Importantly, HMGA1P6 was transcriptionally activated by oncogene MYC in ovarian cancer." (PMID 32127525, 2020). "In addition, HMGA1P6 promotes ovarian cancer aggressiveness through modulating HMGA1 and HMGA2." (PMID 32127525, 2020). "Importantly, MYC transcriptionally upregulated HMGA1P6 as well as HMGA131 in ovarian cancer." (PMID 32127525, 2020). "We further measured HMGA1P6 and HMGA1/2 expression in ovarian cancer cell lines with MYC overexpression or knockdown." (PMID 32127525, 2020). "In agreement with our results, HMGA1P6 and HMGA1P7 expression was also upregulated in anaplastic thyroid and ovarian carcinomas and pituitary tumors, where it significantly correlates with HMGA1 overexpression." (PMID 31096664, 2019). "In ovarian cancer, the MYC oncogene transcriptionally activates HMGA1P6." (PMID 39337410, 2024).
thyroid cancer (2 papers, 2014 to 2019). "Papillary (PTC) thyroid carcinomas, which are well differentiated and poorly aggressive, expressed low levels of HMGA1P6 and HMGA1P7." (PMID 25268743, 2014).
anaplastic thyroid carcinomas (1 paper, 2014). "HEK293 cells and 8505c cells (derived from a human anaplastic thyroid carcinoma) transfected with HMGA1P6- or HMGA1P7-expressing vectors grew significantly faster than the empty vector-transfected cells." (PMID 25268743, 2014). "Moreover, HMGA1P6 and HMGA1P7 were overexpressed in human anaplastic thyroid carcinomas, which are highly aggressive, but not in differentiated papillary carcinomas, which are less aggressive." (PMID 25268743, 2014).
breast carcinoma (1 paper, 2022). "HMGA1P6 and HMGA1P7, two pseudogenes of HMGA1 competing for endogenous RNA, can also lead to cancer when they are dysregulated, and the expression of HMGA1P7 is related to the levels of H19 and IGF2 in breast cancer, which is linked to the high double strand breaks in breast cancer cells." (PMID 35864955, 2022).
pituitary adenomas (1 paper, 2016). "Moreover, functional studies show that the enforced expression HMGA1P6 and HMGA1P7 enhances the proliferation of a pituitary adenoma cell line." (PMID 26895108, 2016). "Interestingly, HMGA1P6 and HMGA1P7 were also overexpressed in human pituitary adenomas where the HMGA proteins play a critical role in their development." (PMID 26895108, 2016). "In particular, HMGA1P6 and HMGA1P7 expression significantly correlates with HMGA1 mRNA in somatotropic and nonfunctioning pituitary adenomas." (PMID 26895108, 2016).
Splenomegaly (1 paper, 2020). Abnormal increased size of the spleen. "Noteworthy, preliminary studies on a mouse strain overexpressing HMGA1P6 pseudogene show that several mice develop a lymphoid pathology characterized by splenomegaly that resembles that found in HMGA1P7-TG mice." (PMID 32341372, 2020).
stomach adenocarcinoma (1 paper, 2020). "TCGA data analysis showed that HMGA1P6 was overexpressed in stomach adenocarcinoma." (PMID 32127525, 2020).
thyroid tumor (1 paper, 2020). A benign or malignant neoplasm affecting the thyroid gland. "HMGA1P6 is reported to be overexpressed in human pituitary and thyroid tumors, and regulates HMGA1 as a competing endogenous RNA15,17." (PMID 32127525, 2020).
cancer (8 papers, 2014 to 2022). A tumor composed of atypical neoplastic, often pleomorphic cells that invade other tissues. "HMGA1 non-coding pseudogenes (HMGA1Ps), HMGA1P6 and HMGA1P7, are two processed pseudogenes that show conserved seed matches for miRNAs targeting the HMGA1 gene and other cancer-associated genes." (PMID 29149041, 2017). "We have recently identified and characterized two pseudogenes (HMGA1P6 and HMGA1P7) of the HMGA1 gene, which has a critical role in malignant cell transformation and cancer progression." (PMID 32341372, 2020). "Although HMGA1P6, HMGA1, and HMGA2 were all overexpressed in HGSOC, only HMGA1P6 and HMGA237 correlated with poor prognosis in cancer patients." (PMID 32127525, 2020). "HMGA1P6 and HMGAP17 act as microRNA decoy for HMGA1 and other cancer-related genes upregulating their protein levels." (PMID 32341372, 2020). "This happens because of shared miRNAs targeting HMGA1P6, HMGA1P7, HMGA1 and other cancer related genes." (PMID 26895108, 2016). "We have recently identified two pseudogenes, HMGA1P6 and HMGA1P7 for the HMGA1 gene whose overexpression has a critical role in cancer progression." (PMID 27874091, 2016). "Taken together, these results indicate that HMGA1P6, HMGA1P7 and HMGA1 expression is correlated with cancer aggressiveness." (PMID 25268743, 2014). "Interestingly, HMGA1P6 and HMGA1P7 also regulate the expression of EZH2, HMGA2, and other cancer-related genes with a critical role in cancer progression by sponging miRNAs able to target these genes." (PMID 35804851, 2022). "Interestingly, HMGA1P6 and HMGA1P7 seem to affect cancer progression also by binding to the same miRNAs that target proteins involved in cancer progression." (PMID 25268743, 2014). "Consequently, it appears that HMGA1P6 and HMGA1P7 expression may contribute to cancer progression by acting as decoys for cancer-related genes other than HMGA1." (PMID 25268743, 2014). "HMGA1P6 and HMGA1P7 are drastically upregulated in ATC but not in PTC, thus contributing to cancer progression." (PMID 35804851, 2022).
tumor (4 papers, 2019 to 2025). "For HMGA1P6, a 2.45-, 15.09-, 5.72-, 7.98-, and 9.15-fold increase was detected in mRNA median expression values of tumor stages IA, IB, II, III and IV, respectively, when compared with normal endometrial samples’ median expression value." (PMID 31096664, 2019). "In OC, HMGA1P6, CTSLP8, and SDHAP1 are known to competitively bind to their paralogs, influencing tumour metastasis and paclitaxel resistance." (PMID 40000433, 2025). "Additionally, a significant increase in HMGA1P6 and HMGA1P7 expression was observed along tumor staging augmentation." (PMID 31096664, 2019).
HMGA1P6 also shares sentences with these, for which no sentence is quoted: breast adenocarcinoma (1 paper); papillary carcinoma (1); pituitary tumor (1).